ANXA3 (annexin A3)
Description:
Inhibitor of phospholipase A2, also possesses anti-coagulant properties. Also cleaves the cyclic bond of inositol 1,2-cyclic phosphate to form inositol 1-phosphate.
Synonyms: ANX3
Tractability: Small molecule: a structure with a bound ligand is known; it has a binding pocket of medium quality. Antibody: its Gene Ontology location is reachable by antibodies, with high confidence; the Human Protein Atlas places it where antibodies can reach. PROTAC: ubiquitination databases record sites on it; its protein half-life has been measured.
Target class: Ion channel; Annexin; Other ion channel
Gene: Protein-coding gene on chromosome 4 (78,551,621 to 78,610,493, forward strand). Ensembl gene ENSG00000138772.
Subcellular location (Human Protein Atlas): Plasma membrane
Pathways (Reactome):
Developmental Biology: Developmental Lineage of Pancreatic Ductal Cells
Gene Ontology:
Molecular function: calcium-dependent phospholipid binding; calcium-dependent protein binding; phosphatidylserine binding; calcium ion binding; phospholipase inhibitor activity
Biological process: defense response to bacterium; neutrophil degranulation; phagocytosis; positive regulation of angiogenesis; positive regulation of endothelial cell migration
Cellular component: cytoplasm; extracellular exosome; membrane; phagocytic vesicle membrane; plasma membrane; specific granule; nucleus; vesicle membrane
Genetic constraint (gnomAD): Loss-of-function variants: 16 observed, 19.54 expected, observed/expected ratio (o/e) 0.82, 90% interval 0.55 to 1.24. The upper end of that interval is the gene's LOEUF score, 1.24, which puts it in group 5 of 6, group 1 being the genes least tolerant of losing a copy. Missense variants: 199 observed, 208.27 expected, observed/expected ratio (o/e) 0.96, 90% interval 0.85 to 1.08. Synonymous variants: 71 observed, 78.15 expected, observed/expected ratio (o/e) 0.91, 90% interval 0.75 to 1.11.
Homologues: Orthologues: chimpanzee ANXA3 (98% identical), macaque ANXA3 (93% identical), rabbit ANXA3 (93% identical), dog ANXA3 (91% identical), guinea pig ANXA3 (90% identical), mouse Anxa3 (90% identical), rat Anxa3 (85% identical), tropical clawed frog anxa3 (76% identical), zebrafish anxa3b (56% identical), zebrafish anxa3a (51% identical), Drosophila melanogaster AnxB9 (45% identical), Drosophila melanogaster AnxB11 (41% identical). Paralogues in human: ANXA4 (52% identical), ANXA11 (51% identical), ANXA6 (50% identical), ANXA1 (50% identical), ANXA8 (49% identical), ANXA8L1 (49% identical), ANXA5 (48% identical), ANXA2 (48% identical), ANXA7 (45% identical), ANXA10 (44% identical), ANXA13 (41% identical), ANXA9 (36% identical).
Diseases named in the same sentence as ANXA3 in open-access papers:
ANXA3 is named in the same sentence as 127 diseases in open-access papers, as found by Europe PMC text mining. Sharing a sentence is not in itself a finding about the gene and the disease. The quoted sentences say what the papers report.
ovarian carcinoma (24 papers, 2012 to 2024). A malignant neoplasm originating from the surface ovarian epithelium. "Annexin A3 (ANXA3) is a protein-coding gene, which is associated with diseases that mainly include ovarian cancer and upper urinary tract uroepithelial carcinoma." (PMID 35464477, 2022). "Annexin 3 (ANXA3) plays a role in cellular growth and signal transduction, and was previously linked to platinum resistance in ovarian cancer." (PMID 23555683, 2013). "Overexpressed ANXA3 could promote tumor proliferation and metastasis in breast, lung, liver, and ovarian cancer, and was associated with chemotherapy resistance." (PMID 35205125, 2022). "Increased levels of Annexin A3 in platinum-resistant ovarian cancer cell lines impart drug resistance by reducing the concentration of platinum compounds within the cell and inhibiting apoptosis." (PMID 38796525, 2024). "It has been proved that the expression of annexin A3 is notably up-regulated in ovarian cancer cells, which are resistant to cisplatin, carboplatin, and platinum." (PMID 37497408, 2023). "Similar approaches employing miRNA and siRNA to probe the effect of ANXA3 depletion have also been applied in in vitro cell-line models of colorectal carcinoma and ovarian carcinoma, which presented consistent results." (PMID 34355022, 2021). "For example, Yin and colleagues found that treatment of ovarian cancer cell lines with cisplatin increases the secretion of exosomes containing annexin A3 in cell culture supernatants and also in sera from ovarian cancer patients." (PMID 32426106, 2020). "In Vitro, ovarian cancer cells expressing higher levels of annexin A3 released increased numbers of EVs, with the protein detected in EVs from cisplatin-resistant cells." (PMID 30682793, 2019). "There is only one study on the role of ANXA3 in chemotherapy resistance, which indicates that the up-regulation of ANXA3 enhanced platinum resistance in ovarian carcinoma." (PMID 29443940, 2018). "ANXA3 is highly expressed in lung, liver, and ovarian carcinoma and is correlated with a poor prognosis of patients." (PMID 29374148, 2018). "In ovarian cancer, the expression of annexin A3 corresponded to the resistance to platinum treatment." (PMID 28771541, 2017). "Studies have demonstrated that ANXA3 is a potential biomarker for carcinogenesis, metastasis and resistance to chemotherapy in many cancers such as ovarian cancer, gastric cancer, breast cancer and liver carcinoma." (PMID 27661117, 2016). "For example, ANXA3 overexpression was found to correlate with enhanced drug resistance in ovarian cancer, promote the development of colorectal adenocarcinoma and pancreatic carcinoma, and facilitate metastasis of lung adenocarcinoma and hepatocarcinoma." (PMID 26475168, 2015). "Recently studies indicated annexin A3 is an inversely correlated marker for colorectal cancer, ovarian cancer, and prostate cancer." (PMID 24884814, 2014). "Yin J reported that sera from ovarian cancer patients contained significantly higher levels of annexin A3 compared with those from normal donors." (PMID 22682408, 2012). "Yan X’s work revealed that increased expression of annexin A3 was a mechanism of platinum resistance in ovarian cancer." (PMID 22682408, 2012). "Exosomes derived from chemoresistant cells show high expression of various resistance-related proteins, including MRP2, Annexin A3, ATP 7A, and ATP 7B; this clearly indicates the potential of exosomes to predict the efficacy of chemotherapy in ovarian cancer patients." (PMID 38796525, 2024). "In addition, studies have shown that overexpression of ANXA3 promotes tumor proliferation in lung, liver, and ovarian carcinomas." (PMID 34221002, 2021). "Likewise, a substantially increased ANXA3 expression has been found in the serum of platinum-resistant ovarian cancer patients compared to the platinum sensitive group, which underscored the value of ANXA3 as a noninvasive marker for drug response prediction." (PMID 34355022, 2021).
ovarian carcinoma (continued). "It has been shown that ANXA3 reduced the accumulation of platinum in ovarian cancer cells." (PMID 29374148, 2018). "Similarly, ovarian cancer cells expressing higher levels of annexin A3 released increased numbers of exosomes, and annexin A3 was detected in exosomes released from cisplatin-resistant cells (SKOV3/Cis) by immunoblotting and immunoelectron microscopy." (PMID 29462943, 2018). "Furthermore, several works revealed that the expression of annexin A3 was related to ovarian cancer." (PMID 22682408, 2012). "The role of annexin A3 in cancer is still not fully understood, however, some proteomic studies have shown that annexin A3 is a biomarker in lung adenocarcinomas, and an overexpression of annexin A3 was detected in platinum-resistant human ovarian cancer cells." (PMID 23170877, 2012). "Similarly, the levels of annexin A3 in the peripheral blood may be a potential predictor for platinum resistance in ovarian cancer." (PMID 29459887, 2018). "Both databases showed that ANXA2, ANXA3, ANXA8, and ANXA11 mRNA expression levels were upregulated in ovarian cancer compared with normal tissues, while ANXA5,ANXA6, and ANXA7 mRNA expression levels were downregulated." (PMID 31474227, 2019). "Recent studies have shown that ANXA2 is highly expressed in ovarian cancer and that ANXA3 and ANXA4 are involved in cisplatin resistance in ovarian cancer." (PMID 31474227, 2019). "ANXA3 was upregulated in platinum-resistant ovarian cancer, whereas ANXA1 and ANXA11 expression was negatively correlated with paclitaxel and cisplatin resistance in ovarian cancer, respectively." (PMID 31474227, 2019). "Annexin A3, P-glycoprotein (P-gp), signal transducer and activator of transcription 3 (STAT3), FAS, DNA methyltransferase-I (DNMT-1), multidrug resistance protein 2 (MRP2), ATP 7A, and ATP 7B are exosomal proteins that promote drug resistance in ovarian cancer cells." (PMID 38796525, 2024). "In addition, we analyzed the differential mRNA expression levels of Annexins between ovarian cancer and normal ovarian tissues using the GEPIA database, which indicated that ANXA2, ANXA3, and ANXA11 mRNA expression levels were significantly upregulated in ovarian cancer." (PMID 31474227, 2019).
prostate carcinoma (15 papers, 2012 to 2025). A carcinoma that arises from epithelial cells of the prostate gland. "ANXA3 was identified as one of the four down-regulated genes involved in prostate cancer progression in a recent study that compared EGFR mutated and non-mutated tumours." (PMID 23555683, 2013). "Regarding its clinical relevance, high ANXA3 expression has been correlated with a poor prognosis in gastric, hepatocellular and breast carcinomas, and it has also been proposed as a diagnostic marker in prostate cancer." (PMID 36247003, 2022). "Furthermore, in a recent study that compared EGFR-mutated and EGFR-wild type tumors, ANXA3 was identified as one of only four downregulated genes involved in prostate cancer progression." (PMID 26475168, 2015). "Accordingly, ANXA3 expression has been found upregulated in breast, colorectal or pancreatic tumors, while downregulated levels have been detected in renal, thyroid or prostate cancers." (PMID 36247003, 2022). "GOLM1, CD24, PSCA, and the gene fusion TMPRSS2-ERG were selected as overexpressed mRNAs in prostate cancer, whereas ANXA3 and SLC45A3 were selected as underexpressed mRNAs in prostate cancer for evaluation." (PMID 33172003, 2020). "The prognostic relevance of ANXA3 for PCa was validated by IHC in prostate tissues and the decreased level of ANXA3 was also found by western blot analysis in urine samples of prostate cancer patients." (PMID 33791193, 2020). "The expression of ANXA3 is reported as an independent factor in the prognosis of prostate cancer and other cancers." (PMID 28497041, 2017). "It has been shown that annexin A3 in urine with a highly specific noninvasive marker for prostate cancer early detection." (PMID 24884814, 2014). "In the human prostate cancer xenograft model, annexin A3 was up-regulated and drug-resistant both in vivo and in the xenograft." (PMID 23170877, 2012). "In addition, some studies demonstrated the tumor oncogene status of ANXA3 in Colorectal carcinoma, pancreatic carcinoma, and Prostatic carcinoma." (PMID 27894078, 2016). "Our scRNA-seq analysis detected greater expression of ANXA3, ANXA2, ANXA2P2, and AHNAK2 in aggressive prostate cancer." (PMID 37476073, 2023). "Detection of prostate cancer implies the presence of prostate specific antigen (PSA) in serum samples and of annexin A3 (ANXA3) protein (<1 fg/mL) as a noninvasive urine biomarker." (PMID 37630022, 2023). "While the expression of other prostate cancer EMT markers HAS-3, AHNAK2, TGFBR2, ANXA2, and ANXA3 was higher in DU145 compared with DUTXR (Fig. 1CII–IV)." (PMID 37476073, 2023).
hepatocellular carcinoma (14 papers, 2012 to 2026). A malignant tumor that arises from hepatocytes. "Furthermore, high levels of ANXA3 in hepatocellular carcinoma has been demonstrated to attenuate the PKCδ/p38 associated apoptosis." (PMID 34355022, 2021). "The up-regulation of ANXA3 promoted the development of colorectal adenocarcinoma and pancreatic carcinoma, and increases the metastatic risk of lung adenocarcinoma and hepatic carcinoma." (PMID 29443940, 2018). "Annexin-A3 is part of a family of calcium-binding proteins known to promote granule fusion in PMNs and to increase neutrophil migration in hepatocellular carcinoma, while vimentin is an intermediate filament found in non-muscle cells." (PMID 34966382, 2021). "Along these lines, AnxA3 monoclonal antibodies sensitized hepatocellular carcinoma to the tyrosine kinase inhibitor sorafenib." (PMID 33810523, 2021). "In hepatocellular carcinoma, ANXA3 has been shown to activate the Notch and MAPK/ERK/JNK signaling pathway, resulting in enhanced cell proliferation and promotion of stem-cell like characteristics." (PMID 34355022, 2021). "In an attempt to ascertain the mechanism of platinum resistance in patients with hepatocellular carcinoma, researchers observed an enhanced degree of resistance to cisplatin-induced cell death in ANXA3-overexpressing tumor cells in vitro and in engrafted mice in vivo." (PMID 34355022, 2021). "Upregulation of ANXA3 was also found in prostate, lung, gastric, and hepatocellular cancers." (PMID 29423100, 2018). "Doxorubicin increased the expression of stemness-related genes, such as epithelial cell adhesion molecule (EpCAM), cytoskeletal 19 (CK19), annexin A3 (ANXA3), and the multidrug-resistance-related gene ABCG2 in hepatocellular carcinoma cells (HCCs)." (PMID 36834846, 2023). "In hepatocellular carcinoma, the overexpression of ANXA2, ANXA3, ANXA4, ANXA5 and ANXA11 promotes proliferation because ANXA2–ANXA5 affect Wnt/β-catenin, MEK-ERK, PI3K/AKT-HIF-α and other pathways." (PMID 36936694, 2023). "In other studies, elevated AnxA3 levels suppressed PKCδ/p38 MAPK-dependent onset of apoptosis and autophagy and might be a target for immunotherapy in hepatocellular carcinoma." (PMID 33810523, 2021). "The results were further validated by RT-PCR, western blot, flow cytometry or immunofluorescent staining which revealed that prominin-1, annexin A1, annexin A3, transgelin, creatine kinase B, vimentin, and EpCAM were indeed highly expressed in the CD133-positive hepatoma cells." (PMID 23170877, 2012).
breast cancer (13 papers, 2015 to 2025). A primary or metastatic malignant neoplasm involving the breast. "ANXA3 promotes heterogeneity of breast cancer stem cells and is associated with chemoresistance; knockdown of ANXA3 prevents lung metastasis in vivo." (PMID 40847127, 2025). "The ANXA3 protein is linked to reduced disease development in breast cancer patients and plays a role in apoptosis regulation in vitro by altering the Bcl-2/Bax balance." (PMID 34571787, 2021). "The study, therefore, associates ANXA3 with prognosis and indicates its possible role in the occurrence, development, and metastasis of breast cancer." (PMID 28497041, 2017). "The findings implicate the expression of ANXA3 with the natural progression of breast cancer and associate it with increased lymphatic metastasis." (PMID 28497041, 2017). "Increased expression of ANXA3 is associated with prognosis of breast cancer." (PMID 28497041, 2017). "However, in SB2−/−;PyMT tumors, a high levels of IFN-γ, which activates the antitumor immune response, and a low levels of Anxa3, which controls cancer cell invasion and lung metastasis, do not support SerpinB2 deficiency causing a delay in PyMT-induced mammary tumor progression." (PMID 35768767, 2022). "In our previous study of transcriptome analysis of mammary tumors of PyMTSB2−/− mice, the expression levels of cancer immune modulated genes (ANXA3, CCL17, CXCL13, CXCR3, IFN-γ, NR4A1, and SEMA3a) were significantly changed." (PMID 38956496, 2024). "In vitro investigations have revealed that ANXA3 overexpression significantly stimulated the invasion and migration of breast cancer cells." (PMID 34355022, 2021). "MTT assay data from this study further indicated a substantially increased sensitivity of ANXA3-knockdown breast cancer cells to doxorubicin and docetaxel." (PMID 34355022, 2021). "Clinically, ANXA3 overexpression has been demonstrated to be correlated with the occurrence of lymph node metastasis and the clinicopathological stages of breast cancer and lung adenocarcinoma." (PMID 34355022, 2021). "These in vivo results suggested that ANXA3 knockdown promoted breast cancer tumor growth but inhibited metastasis." (PMID 29374148, 2018). "In this study, we found that ANXA3 was significantly upregulated in breast cancer tissues at both the mRNA and protein levels, which were verified by qRT-PCR and immunohistochemical staining, respectively." (PMID 29374148, 2018). "Here, we analyzed the uptake of doxorubicin (Dox), which is widely used in breast cancer treatment, in ANXA3-knockdown cell lines by flow cytometry." (PMID 29374148, 2018). "Both human breast cancer cell line MDA-MB-231 and mouse mammary cancer cell line 4T1 showed an increased cellular accumulation of Dox in ANXA3-knockdown cells." (PMID 29374148, 2018). "To examine the function of ANXA3 in breast cancer, we analyzed ANXA3 expression in different human breast cancer cell lines by western blot." (PMID 29374148, 2018). "Throughout the years of investigation Annexin A1 (AnxA1), Annexin A2 (AnxA2), Annexin A3 (AnxA3), Annexin A4 (AnxA4), Annexin A5 (AnxA5), Annexin A6 (AnxA6), and Annexin A8 (AnxA8) have all been identified as potential modulators of breast cancer progression." (PMID 29416802, 2018). "Here, we observed that the expression level of ANXA3 was significantly upregulated in breast cancer tissues." (PMID 29374148, 2018). "To explore the effect of ANXA3 on breast cancer cells, we established ANXA3-knockdown cell lines using MDA-MB-231, MDA-MB-468, and mouse mammary cancer cell line 4T1." (PMID 29374148, 2018). "ANXA3 knockdown suppressed breast cancer cell invasion but promoted proliferation both in vitro and in vivo, which was due to the IκBα-mediated mesenchymal–epithelial transition and the switch of different states of BCSCs." (PMID 29374148, 2018).